HIPK2 (homeodomain interacting protein kinase 2)
Diseases named in the same sentence as HIPK2 in open-access papers (continued):
Sharing a sentence is not in itself a finding about the gene and the disease.
cancer (77 papers, 2009 to 2025). A tumor composed of atypical neoplastic, often pleomorphic cells that invade other tissues. "A direct role of HIPK2 in cancer-associated fibrosis is still an unresolved issue, although its function in fibrosis is starting to be unveiled." (PMID 36831402, 2023). "By using both gain-of-function and loss-of-function approaches, we demonstrate that HIPK2 can elicit a cytoprotective response in cancer cells via NRF2." (PMID 28692050, 2017). "The paradoxical biological behaviors of HIPK2 overexpression in HPV-associated carcinomas are closely linked with the oncogene E6, encoded by high-risk HPV, and HIPK2." (PMID 28607924, 2017). "Dysregulation of HIPK2 has been implicated in increased proliferation, as it is typical in cancer or fibrosis." (PMID 25421593, 2015). "Moreover, it has been reported that HIPK2 promotes the activation of conserved pathways implicated in cancer, such as Wnt and Hippo." (PMID 34065786, 2021). "These experiments suggest a mechanism by which cancer cells in a hypoxic environment can escape chemotherapy-associated (and maybe radiation-associated) apoptosis through the downregulation of HIPK2." (PMID 27542736, 2016). "However, the mechanisms underlying HIPK2 inactivation in this type of cancer remains to be revealed." (PMID 25868975, 2015). "Rare mutations or amplification of the HIPK2 gene in some human cancers have also been reported." (PMID 25868975, 2015). "Advances have been made in understanding the mechanisms underlying chemoresistance in response to HG-induced HIPK2 inhibition, and further development of targeted therapies provides encouraging prospects for clinical application to optimize patient prognosis in different cancers." (PMID 37345014, 2023). "Through these interactions, HIPK2 regulates many cellular functions including cell growth and apoptosis, fibrosis, angiogenesis and inflammation involved in cancer, fibrotic and neurodegenerative diseases." (PMID 39062921, 2024). "HIPK2 plays a key role in cancer biology thanks to the interaction with molecular pathways involved in cancer progression and response to therapies." (PMID 39062921, 2024). "HIPK2 is involved in multiple signaling pathways, including those frequently altered in human cancers." (PMID 39342278, 2024). "HIPK2 plays a key role in the cancer cell response to cytotoxic drugs as its deregulation impairs drug-induced cancer cell death." (PMID 37345014, 2023). "HIPK2, an oncosuppressor able to regulate multiple molecular pathways, has been shown lately to play a role in angiogenesis both in cancer and in other angiogenic diseases." (PMID 36900356, 2023). "In the cancer field, HIPK2 plays a key role in inducing cancer cell apoptosis by modulating several different molecules." (PMID 37345014, 2023). "In this regard, a link between HG and homeodomain-interacting protein kinase 2 (HIPK2) has recently been disclosed in both cancer resistance to chemotherapies and in diabetic complications, which will be summarized in the present review." (PMID 37345014, 2023). "In this review, we will discuss the emerging link between HIPK2 and angiogenesis and how the control of angiogenesis by HIPK2 impinges in the pathogenesis of several diseases, including cancer." (PMID 36900356, 2023).
cancer (continued). "As a proof of principle, the HIPK2 degradation was confirmed by culturing the cancer cells in the presence of hyperglycemic sera derived from patients with T2D compared to normoglycemic sera." (PMID 37345014, 2023). "In an in vitro study, we have shown that the inhibition of HIPK2 in cancer cells induces oxidative stress with increased ROS generation that leads to autophagy-induced fibroblast differentiation into CAF." (PMID 36831402, 2023). "Recently, a role for HIPK2 in angiogenesis has been pointed out, not only in cancer, but also in other angiogenic diseases, and will be summarized below." (PMID 36900356, 2023). "Here, we will briefly summarize the role of HIPK2 in cancer before describing its involvement in fibrosis in detail." (PMID 36831402, 2023). "Noticeably, our study is the first report the role of HDAC5 in the regulation of p16INK4a expression in GC cells, thus providing a novel HDAC5-mediated pathway in cancer, in addition to the TAp63/maspin, HIPK2/HIF1α, and p65/NF-κB pathways." (PMID 37415735, 2023). "In this regard, homeodomain-interacting protein kinase 2 (HIPK2) has recently been disclosed in both high glucose-induced cancer resistance to chemotherapies and in diabetic complications, which will be summarized in the present review." (PMID 37345014, 2023). "The role of HIPK2 in the pathogenesis of cancer and fibrosis is well established, and evidence of its involvement in the homeostasis of multiple organs has been recently emerging." (PMID 34361060, 2021). "We analyzed HIPK2 copy number across the database of the Cancer Cell Line Encyclopedia in cBioPortal and found HIPK2 gain and amplification in human cancer cell lines." (PMID 33613845, 2021). "Further, consistent with its role in angiogenesis during cancer development, HIPK2 acted as a suppressor of angiogenesis in DR as well by negatively regulating HIF1α/VEGF signaling." (PMID 34963484, 2021). "Further investigation, particularly in the context of human cancer cells, is required to define the mechanism of HIPK2-YAP regulation." (PMID 33613845, 2021). "HIPK2 knockout leads to carcinoma in situ or invasive squamous cell carcinoma in a two-stage skin carcinogenesis model." (PMID 33842469, 2021). "In contrast to these observations, HIPK2 has been shown to have prosurvival and proproliferative oncogenic activities in different types of cancers, including a Drosophila leukemia model." (PMID 32093146, 2020). "Homeodomain-interacting protein kinase-2 (HIPK2) is also related to the apoptosis of cancer cells, and the deletion of HIPK2 increases the proliferation potential of cancer cells 53-55." (PMID 32284746, 2020). "Conflicting roles of HIPK2 have also been reported in relation to pathologic conditions, such as cancer and tissue fibrosis." (PMID 32093146, 2020). "Further work will be needed to better understand and discriminate the consequences of HIPK2 dysfunctions leading to higher MBR levels on cancer formation/progression." (PMID 33043004, 2020). "In mouse, in transformed fibroblasts and in cancer cells of different origins, HIPK2 inactivation leads to increased tumorigenicity." (PMID 33043004, 2020). "By contrast, Hipk2 is elevated in certain cancers, including cervical cancers, pilocytic astrocytomas and colorectal cancer cells, and in other diseases, such as thyroid follicular hyperplasia." (PMID 29208636, 2018).
cancer (continued). "In detail, they confirmed that overexpression of HIPK2 sensitized chemoresistant cancer cells to cisplatin by inhibiting Wip1 expression." (PMID 28107201, 2017). "Hypoxia helps cancer cells to resist chemotherapy, whereas HIPK2 mediated repression of HIF-1α activity confers sensitization of chemoresistant cells with drug induced apoptosis." (PMID 28107201, 2017). "HIPK2 can serve as a novel biomarker in tumors as well as a potential target for anti-cancer therapies." (PMID 28107201, 2017). "HIPK2 is activated by various anti-cancer drugs, including cisplatin (CDDP), adriamycin (ADR) and roscovitin, to form HIPK2/p53Ser46 apoptotic signaling pathway." (PMID 28107201, 2017). "Homeodomain interacting protein kinase 2 (HIPK2) is a nuclear serine/threonine kinase that is considered a central switch in driving cancer cells toward apoptotic cell death upon genotoxic stress." (PMID 27901482, 2017). "HIPK2 dysregulation has been shown to contribute to proliferative diseases, such as cancer and tissue fibrosis." (PMID 28060750, 2017). "Apoptosis can be initiated by repressing HIPK2 degradation, strongly suggesting that HIPK2 is a potential target for cancer therapy." (PMID 28107201, 2017). "As observed with cancer cells, both HUVECs and HFs showed clear and comparable repression of the Hipk2-FL isoform with all the employed e8-specific siRNAs and significant loss of viability only with the e8-siRNA#1." (PMID 26625198, 2016). "SRSF3 reportedly modulated the alternative splicing of several apoptosis-related genes, such as caspase-2 (Casp2), programmed cell death 4 (PDCD4), and homeodomain-interacting protein kinase-2 (HIPK2) in distinct cancer cells." (PMID 27983653, 2016). "Activation of the AR regulator HIPK2 (Homeodomain-Interacting Protein Kinase 2) by genotoxic stress triggers apoptosis in part through phosphorylation of CtBP1, which causes CtBP1 degradation; loss of this signaling could plausibly cause predisposition to multiple forms of cancer." (PMID 26485759, 2015). "As a newly found auxiliary transcription inhibition factor, HIPK2 has been suggested to affect many aspects of cancer." (PMID 25282590, 2014). "In 100 cases of human CRC cancer samples, 74 expressed low levels of HIPK2 protein (−and +) and 26showed high expression (++ and +++)." (PMID 25282590, 2014). "HIPK2 inhibition suppresses the adriamycin-induced apoptosis in chemoresistant cancer cells, whereas overexpression of HIPK2 triggers apoptosis in chemoresistant cells, associated with induction of p53Ser46-target gene AIP1." (PMID 24846322, 2014). "This review will focus on the last updates about HIPK2 contribution in tumorigenesis and cancer treatment." (PMID 22889244, 2012).
cancer (continued). "However, recent findings revealed a complex role of HIPK2 in different cancer types that strongly depends on tissue and cellular context and can determine either oncosuppressive or oncogenic effects." (PMID 39342278, 2024). "In this regard, targeting NRF2 in tumors might be a useful strategy to restore cancer chemosensitivity and likely HIPK2 apoptotic activity." (PMID 39062921, 2024). "The role of HIPK2 in cancer has been previously well reviewed." (PMID 39062921, 2024). "Recently, it has been shown that microRNAs (miRNAs) may regulate HIPK2 both at the mRNA and the protein level, having an effect on cancer progression and angiogenesis as well as on other diseases." (PMID 37345014, 2023). "HIPK2 is an evolutionary conserved serine/threonine kinase with multifunctional roles in stress response, embryonic development and pathological conditions, such as cancer and fibrosis." (PMID 36935052, 2023). "In this way, the autoregulatory loop between HIF-1 and HIPK2 modifies the downstream pathways regulated by both proteins, and its balance may dictate the cancer survival/cell death outcome in response to therapies." (PMID 37345014, 2023). "HIPK2 activity has been mainly studied in the cancer biology field." (PMID 36831402, 2023). "Similarly, HIPK2 plays a role in the cellular response to DNA damage, and its expression levels can serve as prognostic markers for certain cancers." (PMID 37888480, 2023). "Homeodomain-interacting protein kinase 2 (HIPK2), a multifaceted protein that regulates different molecular pathways, is involved in the negative regulation of cancer growth, and may be considered a “bona fide” oncosuppressor molecule." (PMID 36900356, 2023). "These functions suggest a significant role of HIPK2 in cancer." (PMID 33842469, 2021). "This, along with the observed autophagic flux reduction, which is in the range of reduction reported between cancer and normal cells, supports the hypothesis that HIPK2 modulates the MBR autophagy-mediated degradation." (PMID 33043004, 2020). "The expression levels of MDR1 mRNA and P-glycoprotein (P-GP) and homeodomain-interacting protein kinase-2 (HIPK2) proteins are upregulated after upregulating the miR-27a level in cancer cells, while the sensitivity to paclitaxel is decreased in cancer cells transfected with miR-27a mimics." (PMID 31572683, 2019). "In summary, HIPK2 inhibits cancer cell tumorigenesis, and promotes pro-apoptotic gene expression." (PMID 28107201, 2017). "HIPK2 may be an attractive biomarker and a therapeutic target, particularly in patients with cancer and HPV infection." (PMID 28607924, 2017). "Zinc restored protein levels of HIPK2 and the chemo-sensitivity in cancer cells." (PMID 28107201, 2017). "Taken together, our results suggest that HG may play a critical role in reducing the apoptotic response in cancer cells by promoting HIPK2 degradation." (PMID 27901482, 2017).
cancer (continued). "In addition, FAM84B gene expression is suppressed in cell line transfected with HIPK2 expression vector, which inhibits cancer cell invasion by down-regulating vimentin expression." (PMID 25980316, 2015). "Together, these data suggest a possible scenario in which Siah2 targeting of HIPK2 protects cancer cells from apoptosis induction while inhibition of Siah2 could increase HIPK2 abundance thus sensitizing cancer cells to cell death agents." (PMID 21586138, 2011). "Thus, Zn2+ supplementation to HIPK2 depleted cancer cells determines a regain of the wt53 protein conformation and restoration of DNA binding and transcriptional activities in response to genotoxic agents in vitro and in vivo." (PMID 20876941, 2010). "Therefore, a better understanding of the mechanistic interplay between NRF2 and HIPK2 could help to elucidate not only the pro-survival/apoptotic outcome in cancer, especially in response to therapeutic agents, but also the induction of fibrosis." (PMID 36831402, 2023). "In addition, the other identified common kinases in ALS and human cancers, including the homeodomain-interacting protein kinase 2 (HIPK2), is a serine–threonine kinase, that participates in the regulation of gene expression, signal transduction, and apoptosis regulations." (PMID 36590916, 2022). "Moreover, certain human cancers display elevated levels of HIPK2 within tumorous tissue." (PMID 29208636, 2018). "Furthermore, our results suggest that modulation of either HIPK2 levels or activity could be exploited to impair NRF2-mediated signalling in cancer cells, and thus sensitise them to chemotherapeutic drugs." (PMID 28692050, 2017). "Thus, this study reveals that HIPK2/Wip1 is an effective drug target for enhanced cancer therapy." (PMID 24846322, 2014). "In addition, the HIPK2-induced H2B activation reveals an unpredicted function of the extra-chromosomal activity of the H2B core histone, whose requirement for faithful cytokinesis can become a target for anti-cancer drugs." (PMID 22889244, 2012). "Thus, HIPK2 could be useful in cancer therapy to enhance the effectiveness of chemotherapeutic drugs." (PMID 19128456, 2009). "In that setting, HIPK2 has been shown to induce some antioxidant target genes that it has in common with NRF2 (i.e., NQO1, HO-1), promoting cancer cell survival." (PMID 39062921, 2024). "It has been reported that PERK/ATF4 induces transcription and expression of the ubiquitin ligases SIAH1/2 in cancer cell lines.To identify the link among PERK, ATF4, SIAH2 and HIPK2, knockdown of genes by siRNA was carried out." (PMID 37268944, 2023).